ELL2P1 (elongation factor for RNA polymerase II 2 pseudogene 1)
Gene: Processed pseudogene on chromosome 1 (158,175,850 to 158,177,755, reverse strand). Ensembl gene ENSG00000227295.
Diseases named in the same sentence as ELL2P1 in open-access papers:
ELL2P1 is named in the same sentence as 1 disease in open-access papers, as found by Europe PMC text mining. Sharing a sentence is not in itself a finding about the gene and the disease.
ELL2P1 shares sentences with these, for which no sentence is quoted: diabetes (1 paper).